WWP1 (WW domain containing E3 ubiquitin protein ligase 1)
Diseases named in the same sentence as WWP1 in open-access papers (continued):
Sharing a sentence is not in itself a finding about the gene and the disease.
cancer (continued). "Concomitantly, TXNIP destabilization in WWP1‐overexpressing leukemic cells would restrict its capacity to inhibit intracellular glucose transport and consumption, further contributing to the promotion of cancer cell survival and fitness." (PMID 39364720, 2025). "However, almost all reports on the expression mechanisms of WWP1 have used cancer models, and little is known about WWP1 regulation in metabolic disorders." (PMID 41009733, 2025). "Transforming growth factor β (TGFβ) and tumor necrosis factor α (TNFα) stimulate transcription of the WWP1 gene via unknown mechanisms in cancer progression." (PMID 41009733, 2025). "As a result, WWP1 depletion promotes cell cycle arrest and promotes cancer cell survival." (PMID 39364720, 2025). "WWP1 depletion in those cancers demonstrated growth-inhibitory effects in vivo and in vitro." (PMID 39656237, 2025). "Molecular basis of WWP1 deregulation include altered transcription, DNA copy number gain, and amplification, whereas somatic and germline mutations are not frequent in cancer cells." (PMID 39364720, 2025). "Additionally, it provides an updated analysis of recent research on WWP1’s role in various cancers, highlighting its therapeutic potential in oncology." (PMID 39949609, 2024). "Research has identified the WWP1 gene on chromosome 8q21, a region frequently amplified in various cancers, including PCa, suggesting that WWP1 may function as an oncogene in PCa." (PMID 39949609, 2024). "In conclusion, WWP1 emerges as a promising target for many diseases, including cancer." (PMID 38129384, 2023). "Finally, we highlight WWP1’s role in normal physiology, contribution to pathological conditions, and therapeutic potential for cancer and other diseases." (PMID 38129384, 2023). "Moreover, these molecules can be specifically tailored to target oncogenic deubiquitinases (DUBs), such as ATXN3L and BAP1, which are known to destabilize the tumor-suppressive protein WWP1 in certain cancer types." (PMID 38129384, 2023). "WWP1 promotes cancer stemness in NSCLC by inducing ubiquitination and stabilization of EGFR." (PMID 38129384, 2023). "Preclinical data suggest that WWP1 could be a potential therapeutic target for cancer and various other diseases." (PMID 38129384, 2023). "As a result, targeting WWP1 may hold promise as a therapeutic approach for overcoming resistance to treatment in various cancer types." (PMID 38129384, 2023). "By contrast, several studies have shown that WWP1 negatively regulates PTEN in cancers." (PMID 37032433, 2023). "When ARHGAP24 is highly expressed in cancer cells, it may recruit WWP1 to form protein complexes and then promote PKM2 degradation." (PMID 36168627, 2022). "In the following paragraphs, we describe how multiple factors such as YAP, TAZ, BAP1, Notch-1, and noncoding RNAs, including miR-16-5p, miR-21-5p, miR-30a-5p, miR-129-3p, miR-129-5p, miR-452, miR-584-5p, and lncRNA SNGH12, regulate the expression of WWP1 in human cancer." (PMID 34226507, 2021). "Dysregulation of WWP1 expression and its roles in other cancers needs to be further elucidated." (PMID 34712671, 2021). "Moreover, we summarize the both oncogenic and tumor suppressive functions of WWP1 in a variety of human cancers." (PMID 34226507, 2021). "The undermentioned regulation mechanisms may account for the reduced expression of WWP1, which is likely to function as a tumor-suppressive E3 ligase in these cancers." (PMID 34712671, 2021). "Most studies reveal that WWP1 exerts tumor promotion functions in various types of cancers." (PMID 34226507, 2021). "Besides that, WWP1 can be upregulated at the transcriptional and post-transcriptional levels in cancers." (PMID 34712671, 2021). "Moreover, the abnormal regulations of WWP1 are also involved in multiple diseases, like inflammation, neurological disorders, aging, and cancers." (PMID 34226507, 2021). "On the other hand, WWP1 is downregulated in several cancer types and may play as a tumor suppressor." (PMID 34712671, 2021).
cancer (continued). "Different WWP1 isoforms may as well account for discrepant roles of this gene in different tissues or cancer types." (PMID 34712671, 2021). "WWP1 contains two WW domains that have been shown to recruit and modulate the activity of cancer related proteins like Runt-related transcription factor 2 (RUNX2), RING finger protein 11 (RNF11) and large tumor suppressor kinase 1 (LATS1) via their proline-rich (PY) motifs." (PMID 33869064, 2021). "Finally, a natural compound called indole-3-carbinol was identified as a natural inhibitor of WWP1, thereby identifying a potential therapeutic strategy for cancer prevention and treatment through reactivation of PTEN function." (PMID 33659963, 2020). "Moreover, SNHG12 was also reported to be involved in the tumorigenesis of other cancers by interacting with miR-129-5p/WWP1, miR-195/CCNE1, miR-125-5p/MDM4, miR-326/E2F1, and miR-15a-5p/SALL4 axes." (PMID 33294456, 2020). "Note that overexpression of the wild-type (WT) WWP1 only showed negligible effect on cell migration and proliferation compared with that observed for the mock group, indicating that the cancer-related migration and proliferation effects of WWP1 are tightly coupled to its ligase activity." (PMID 31320636, 2019). "Overall, these results indicated that WWP1 may influence cancer progression by promoting cell proliferation and migration via the regulation of ∆Np63α turnover." (PMID 31320636, 2019). "Human WWP1 is localized on chromosome 8q21, a region frequently amplified in many human cancers." (PMID 26506518, 2015). "WW domain-containing E3 ubiquitin protein ligase 1 (WWP1) has been speculated to play important roles in the development of several kinds of cancers." (PMID 26506518, 2015). "To understand whether LATS1 stability is also regulated by other members of the NEDD4-like family of E3 ligases, we selected 4 ubiquitin ligases including NEDD4, WWP1, Smurf1 and Smurf2 that have been shown to be involved in the development of human cancers." (PMID 23573293, 2013). "Genetic and functional analyses in human cancers have shown that WWP1 is a potential oncogene." (PMID 22629406, 2012). "WWP1 variants have been shown to cause cancer in many patients without PTEN deficiency." (PMID 39144161, 2024). "In summary, the intricate interplay between WWP1, its role in cancer and viral-related processes, and the potential therapeutic implications of compounds like I3C highlight the multifaceted scope of its biological roles and the promise it could hold for future therapeutic development." (PMID 38129384, 2023). "Other E3 ligases, mainly the HECT domain E3 ligases such as WWP1, WWP2, NEDD427–29 also adopt similar closed autoinhibited state, in which its multiple WW domains sequester HECT using a multi-lock mechanism and phosphorylation of linker or cancer associated mutation relieve autoinhibition." (PMID 38104184, 2023). "Finally, we provide the perspectives regarding WWP1 in cancer development and therapies." (PMID 34226507, 2021). "Finally, we provide the perspective regarding WWP1 in cancer development and therapies." (PMID 34226507, 2021). "It has been reported that the E3 ubiquitination ligase WWP1 can ubiquitinate PTEN, inhibit its activity, and activate the PIK3CA/AKT signaling pathway to increase the occurrence and development of cancer." (PMID 40075587, 2025). "The HECT E3 ubiquitin ligases 1 (WWP1) and 2 (WWP2) are responsible for the ubiquitin-mediated degradation of key tumour suppressor proteins and are dysregulated in various cancers and diseases." (PMID 39223706, 2024).
cancer (continued). "Instead, WWP1 modulates RNF11’s ability to downregulate ErbB2 and EGFR, highlighting its complex role in cancer biology." (PMID 39949609, 2024). "While WWP1 has been extensively studied for its role in cancer via ubiquitin-mediated degradation, WWP2 shares structural and functional similarities with WWP1 but performs distinct roles, particularly in regulating the cell cycle and protein degradation." (PMID 39949609, 2024). "High expression levels of WWP1 and WWP2 frequently correlate with poor prognosis, increased tumor invasiveness, and reduced survival rates in cancers such as breast, colorectal, lung, liver, and ovarian cancers." (PMID 39949609, 2024). "In summary, the mutation status and RNA expression levels of WWP family members, particularly WWP1 and WWP2, are emerging as important prognostic factors in various cancers." (PMID 39949609, 2024). "Its anti-cancer properties have been attributed at least in part to its inhibitory activity of proto-oncogenic HECT E3-ubiquitin ligases such as NEDD4 and WWP1." (PMID 39519210, 2024). "WWP1 regulates various signaling pathways, such as PI3K/AKT, TGF-β, and Hippo cascades, thus promoting cancer cell proliferation." (PMID 38129384, 2023). "WWP1 exerts the autophagy inhibitor and the tumor promotor roles in AML cancer cells where it negatively regulates the phagophore nucleation and elongation likely via targeting ATG7 and LC3." (PMID 36918822, 2023). "Levels of circWAC and WWP1 were found to be downregulated, while miR-142 was highly expressed in the tumor tissues derived from circWAC-silenced MDA-MB-231 cancer cells." (PMID 37568787, 2023). "There was a notable decline in the migratory and invasive properties of WWP1-silenced PC3 and DU145 cancer cells." (PMID 37568787, 2023). "Hence, WWP1 might represent a promising therapeutic target for these cancers." (PMID 38129384, 2023). "WWP1 regulates cell growth, proliferation, apoptosis, EMT, migration, invasion, metastasis, drug resistance, and cancer stemness by targeting various substrates for polyubiquitination." (PMID 38129384, 2023). "The ubiquitin E3 ligase WWP1 is another member of the NEDD4 family showing an important role in the maintenance and development of cancer, acting as either oncoprotein or tumor suppressive." (PMID 36918822, 2023). "Importantly, WWP1 inhibition using small molecule inhibitors such as Indole-3-Carbinol (I3C) and Bortezomib or siRNAs leads to significant suppression of cancer growth and healing of bone fractures, suggesting that WWP1 might serve as a potential therapeutic target for several diseases." (PMID 38129384, 2023). "Specifically, two members of a subgroup of HECT-E3 ligases, known as C2-WW-HECT (NEDD4-like), have been identified to be most involved in cancer: NEDD4 and WWP1." (PMID 37259386, 2023). "In addition, WWP1 could mediate the resistance of doxorubicin and cisplatin in human cancer cells." (PMID 34226507, 2021). "Indeed, intriguing insights into PTEN-associated cancers have been attributed to mechanisms associated with PTEN ubiquitination, a recent example of which is a report demonstrating that the ubiquitin E3 ligase WWP1 can inhibit PTEN function by blocking its dimerisation and membrane recruitment." (PMID 33659963, 2020). "In particular, evidence linking WWP1 to the regulation of cellular redox state in cancer cells is still lacking." (PMID 39364720, 2025). "Mechanistically, as reported in other cancer types, PTEN is a target of WWP1 in PDAC cells." (PMID 39656237, 2025). "Having established a role of CYYR1 in WWP1 degradation, we then set out to explore the role of this novel protein in these cellular processes related to cancer progression." (PMID 39059493, 2024).
cancer (continued). "HCC, one of the most prevalent cancers worldwide, is marked by significantly elevated WWP1 protein levels in tumor tissues compared to adjacent non-cancerous tissues." (PMID 39949609, 2024). "WWP1 knockdown induces cell death in MCF7 and HCC1500 ER-positive breast cancer cells by activating the extrinsic apoptotic pathway, whereas WWP1 overexpression promotes cancer survival." (PMID 38129384, 2023). "A systematic search in different electronic databases indicated that, among HECT-type E3 ligases, members of the NEDD4 family including NEDD4-1, NEDD4L, SMURF-1, SMURF-2, WWP1, WWP2, and ITCH have been investigated in many various cancers with defective autophagy, as reviewed in next sections." (PMID 36918822, 2023). "They found that the tumor suppressor PTEN was reactivated for cancer treatment through inhibition of the MYC-WWP1 pathway, and further identified a derivative of cruciferous vegetables (I3C) as a potent WWP1 inhibitor via PTEN reactivation, leading to suppression of tumorigenesis." (PMID 36127339, 2022). "Via a plethora of substrates, WWP1 regulates kaleidoscopic signaling pathways such as TGFβ, EGF, WNT, PI3K-AKT, and Hippo pathways, consequently promoting or inhibiting neoplasia and progression of diverse cancers." (PMID 34712671, 2021). "Therefore, it is possible WWP1 and Itch regulates LATS1 stability in different cancer types and physiological conditions." (PMID 23573293, 2013). "Recent studies have shown that I3C-mediated inhibition of WWP1 can restore PTEN stability and suppress tumor progression in MYC-driven cancer models, implying how therapeutic targeting of the WWP1-PTEN axis could be effective against a broad spectrum of cancers driven by the MYC oncogene." (PMID 40002221, 2025). "Although these studies could not pinpoint the signaling cascade responsible for the cancer-promoting effect, they suggest the mechanisms may involve a negative regulation of TGFβ signaling by WWP1, which may promote cell cycle arrest and induce apoptosis." (PMID 33418880, 2021). "According to our findings, we can propose a model according to which the overexpression of WWP1 in AML blasts could lead to increased Trx activity through accelerated TXNIP degradation, thus lowering intracellular ROS levels and favoring survival of cancer cells." (PMID 39364720, 2025). "In addition, our results suggest that in addition to mRNA down-regulation by promoter hypermethylation, down-regulation of LATS1 at the protein levels through WWP1-mediated ubiquitination and degradation may be a novel mechanism by which LATS1 is down-regulated in various cancers." (PMID 23573293, 2013).
tumor (43 papers, 2011 to 2025). "The correlation between WWP1 expression in tumor tissues and clinical parameters of patients was analyzed, and it was observed that high expression of WWP1 was associated with higher Gleason score and T stage in patients." (PMID 38997648, 2024). "The E3 ubiquitin ligase WWP1 has demonstrated prognostic and therapeutic value as a tumor susceptibility gene in breast, liver, and colorectal cancers." (PMID 39014007, 2024). "In summary, this study demonstrated that WWP1 was upregulated in ICC tumor tissues compared to paired non-tumor tissues, and high WWP1 expression was associated with a poor prognosis." (PMID 35264565, 2022). "High expression of WWP1 was linked to tumor size, T classification, TNM stage, distant metastasis, and poor survival." (PMID 34226507, 2021). "Bioinformatics analysis revealed WWP1, a well-studied tumor oncogene associated with many malignancies, to be a potential target of miR-584-5p." (PMID 28431583, 2017). "Our study demonstrates that miR-584-5p is associated with tumor size and that miR-584-5p suppresses GC development and progression in a WWP1-dependent manner." (PMID 28431583, 2017). "In addition, our work shows molecular details about the tumor-promotion effect of WWP1 by inducing K63-linked K689 ubiquitination of EGFR, which subsequently promotes EGFR recycling and maintains EGFR stability." (PMID 32694521, 2020). "WWP1 expression was also found to be associated with tumor size exceeding 3 cm in GC patients." (PMID 28431583, 2017). "Tumor BC_2R harbored a mutation in WWP1 that encodes an E1 ligase." (PMID 27383411, 2016). "Moreover, WWP1 dysregulation is associated with tumor progression." (PMID 39059493, 2024). "To evaluate the anti-tumor effects of WWP1 inhibition in vivo, we conducted a xenograft assay using subcutaneously transplanted PDAC cells in mice." (PMID 39656237, 2025). "Recently, WWP1 inhibition was reported to suppress tumor development and cell proliferation by activating the PTEN function." (PMID 39656237, 2025). "PTEN silencing abrogated the growth-inhibitory effects in WWP1-depleted cells, suggesting that the anti-tumor effects of WWP1 inhibition are mediated through PTEN activation." (PMID 39656237, 2025). "This provides critical insights for predicting the anti-tumor effects of WWP1 inhibition in combination with PI3K-AKT pathway inhibitors, potentially improving the prognosis of PDAC." (PMID 39656237, 2025). "Tumor necrosis factor (TNF)-related apoptosis-inducing ligand (TRAIL), which induces tumor-specific apoptosis through caspase-8 activation, faces resistance mechanisms involving WWP1." (PMID 40535763, 2025). "Mechanistically, WWP1 regulates the stability and function of several tumor-suppressive proteins by ubiquitinating them, including p27, RNF11, and SMADs." (PMID 39656237, 2025). "In contrast, HIPK3 overexpression promoted tumor growth, and partially reversed the inhibitory effects of WWP1 knockdown on tumor growth." (PMID 40280416, 2025). "The biological functions of WWP1 in various tumors remain contentious, as it can function both as an oncogene and a tumor suppressor." (PMID 40280416, 2025). "WWP1 inhibition enhances the anti-tumor effects of PI3K-AKT pathway inhibitors through PTEN activation." (PMID 39656237, 2025). "PCa patients were divided into two cohorts of high WWP1 expression (n = 19) and low WWP1 expression (n = 19) based on the mean WWP1 IHC scores in the tumor tissues." (PMID 38997648, 2024). "WWP1 demonstrates a dual function, acting predominantly as an oncogene in tumors but occasionally as a tumor suppressor." (PMID 39949609, 2024). "PTEN membrane localization can be restored by genetic or chemical inhibition of WWP1, and tumor growth can be inhibited in vitro and in vivo in cooperation with PI3K inhibitors." (PMID 39144161, 2024).